APOB (apolipoprotein B)
Diseases named in the same sentence as APOB in open-access papers (continued):
Sharing a sentence is not in itself a finding about the gene and the disease.
atherosclerosis (continued). "Apolipoprotein B is mostly known as the LDL carrier protein, and it is an important contributor to atherosclerosis and cardiovascular disease." (PMID 33731775, 2021). "The recent development of technologies to detect ApoB-specific T cells at the single cell level, including MHC-class II tetramers, has greatly widened our understanding of adaptive immune mechanisms in atherosclerosis." (PMID 33669769, 2021). "Apolipoprotein B, as a structural component of LDL-C, VLDL-C, and TG, plays a key role in early atherosclerosis." (PMID 34066182, 2021). "These images of atherosclerotic lesions from the T1D mouse model of accelerated atherosclerosis show that APOC3 immunoreactivity is present in the artery wall and substantially colocalizes with apolipoprotein B (APOB)." (PMID 33554869, 2021). "Altogether this indicates that the apoB/apoA-1 ratio, reflecting the balance between atherogenic and anti-atherogenic particles, is a useful risk indicator for coronary heart disease and the development of atherosclerosis, in a similar manner as LDL-C and non-HDL-C or apoB only." (PMID 34851955, 2021). "Apolipoprotein B100 (ApoB100), a composition of low-density lipoprotein (LDL), is a major factor leading to atherosclerosis." (PMID 34471467, 2021). "We confirmed that ApoB ASO treatment led to reduction in plaque macrophages and promoted resolution of atherosclerosis." (PMID 33720008, 2021). "Atherosclerosis-related antigens were detected in human and experimental models of atherosclerosis, including oxidized LDL (oxLDL), apolipoprotein B-100 (ApoB100) and heat shock proteins." (PMID 33383733, 2020). "In contrast, patients with subclinical atherosclerosis harbored a substantial increase in T-bet and RAR-related orphan receptor gamma-T(RORγT)-expressing ApoB+ T cells, TFs typical of proatherogenic TH1 cells and TH17 cells." (PMID 33266027, 2020). "Compelling evidence indicates that apolipoprotein B (ApoB), the core protein of LDL, serves as such an atherosclerosis-specific autoantigen." (PMID 32650487, 2020). "Numerous studies have demonstrated the involvement of LDL and apoB, for example, very low-density lipoproteins (VLDL) and their residues in the formation of atherosclerosis." (PMID 31212708, 2019). "There is a linear correlation between the levels of circulating cholesterol-rich apoB-100 lipoproteins and the content of immune-detectable LDL in early atherosclerosis in humans, as shown by Smith and Slater." (PMID 29966388, 2018). "Its reaction with lysine residues forms lysine–lysine cross-links, which have been detected in apolipoprotein B (apoB) fragments of oxidized low-density lipoprotein (oxLDL), and has been hypothesized to interrupt the interaction between oxLDL and macrophages, and thereby enhance atherosclerosis." (PMID 30513640, 2018). "Additionally, compared to mouse, the primary responding molecules (APOA4 and APOB) had more similar expression change in high-fat fed rabbits and human atherosclerotic patients, suggesting rabbit is a better model to simulate the lipoprotein metabolism of human atherosclerosis." (PMID 30067832, 2018). "In particular, downregulation of Ldl (ApoB) and IL-1 was observed, affecting the LXR-RXR and atherosclerosis signalling pathways." (PMID 30385846, 2018). "Apolipoprotein B100 (ApoB100) is a major component of low-density lipoprotein (LDL) and its oxidation can trigger inflammation in vascular endothelial cells leading to atherosclerosis." (PMID 30242056, 2018). "Other markers of atherosclerosis, such as LDL cholesterol, adiponectin, and apolipoprotein B48 were comparable between the two groups." (PMID 28683796, 2017).
atherosclerosis (continued). "ApoB is the main protein constituent of very low-density lipoprotein (VLDL) and LDL and is known to be involved in atherosclerosis and cardiovascular disease." (PMID 28045435, 2017). "We first studied the effect of oral administration of individual peptides derived from ApoB and HSP60 and their combination (ApoB+HSP60) on development of atherosclerosis in ApoBtm2Sgy/Ldlrtm1Her mice." (PMID 23505495, 2013). "Our study showed a synergistic effect of immunization with a combination of ApoB and HSP60 peptides in preventing early atherosclerosis." (PMID 22957222, 2012). "Recent studies has shown A. caudatus extract decreased the most important risk factors of cardiovascular diseases the serum lipoproteins, apoB and Ox-LDL and inflammatory factors prevented atherosclerosis." (PMID 21619685, 2011). "Due to its role in the assembly of the atherogenic lipoprotein particles LDL and Lp(a), APOB has become a prime target for therapeutic interventions to reduce LDL and Lp(a) levels, and therefore perhaps to retard atherosclerosis." (PMID 17233885, 2007). "ApoB serves as a component of serum intermediate-density lipoprotein (IDL), very low-density lipoprotein (VLDL), and LDL-C particles, potentially contributing to atherosclerosis." (PMID 40379620, 2025). "Its presence may indicate a high concentration of apolipoprotein B (ApoB), the protein component of atherogenic lipoproteins, particularly in LDL, which is an important biochemical marker for atherosclerosis, even at younger ages." (PMID 41259573, 2025). "APOB and MMP1 were also added as core targets since they are both targets with large differential expression in GSE100901 and share the same metabolic pathway of lipids and atherosclerosis." (PMID 38905402, 2024). "A postmortem study revealed that the pericardial fluid of people with severe atherosclerosis contained higher amounts of ApoB than those without atherosclerosis." (PMID 38339027, 2024). "Central to atherosclerosis is the retention of cholesterol-rich lipoproteins, particularly low-density lipoprotein (LDL) and other apolipoprotein B (ApoB)-containing particles, within the arterial wall, initiating an inflammatory cascade that promotes lesion development." (PMID 39275181, 2024). "Another aim of the study was to investigate differences in the relationships between atherosclerosis-related lipid parameters in men and women with LDL/ApoB < 1.2, which could lead to a better stratification of cardiovascular risk." (PMID 39420941, 2024). "Thus, our dataset allowed assignment of APOB reactivity to TCR sequences within complex repertoire of T cells, enabling tracking and annotation of atherosclerosis-related clones in the general population." (PMID 38571941, 2024). "While apoB is not available in all laboratories like LDL-C or HDL-C, it plays a causative role in atherosclerosis progression and should be measured in individuals with dyslipidaemia." (PMID 39598108, 2024). "The levels of APOB protein have been found to have a positive correlation with hypercholesterolemia, and a decrease in APOB synthesis has been shown to significantly reduce LDL-C levels and the prevalence of atherosclerosis." (PMID 37892520, 2023). "Atherosclerosis advances primarily as a result of lipids, especially cholesterol-laden low-density lipoprotein (LDL) and other lipoprotein particles that contain apolipoprotein B (apoB), such as very low-density lipoprotein(a) [Lp(a)]." (PMID 38024867, 2023). "CD4+ T cells could proliferate and secrete cytokines to promote atherosclerosis when restimulated with low-density lipoprotein cholesterol (LDL-C) and apolipoprotein B (ApoB)." (PMID 37461090, 2023). "Atherosclerosis results from an influx of cholesterol-rich low-density lipoprotein (LDL) particles, coated with apolipoprotein B (ApoB) protein, in the intimal layer of the arterial wall in atherosclerosis-susceptible regions of the arterial tree, such as in arterial bifurcations." (PMID 37513323, 2023).
atherosclerosis (continued). "Non-diabetic atherosclerosis patients have higher AGE-apolipoprotein B (apo B) levels and AGEs have been observed in atherosclerotic plaques in humans as well as in animal models." (PMID 36760567, 2023). "The unique structure of the Lp(a) may form the link between atherosclerosis (which is partially mediated by the LDL sample) and thrombotic (partially mediated by apolipoprotein B), and contribute to IS." (PMID 36303257, 2022). "Without the entry of cholesterol-containing apoB-lipoproteins into the arterial wall, there is no atherosclerosis." (PMID 35310965, 2022). "Despite the fact that approximately 90% of apoB particles in circulation are resident in LDL particles, apoB is of increasing interest in atherosclerosis research, due to its ability to predict the atherogenic risk, which is more accurate than other markers such as LDL-C and HDL-C." (PMID 35371605, 2022). "In addition to LDL-C levels, other lipid components, such as Apolipoprotein-B (ApoB), Apolipoprotein A-1 (ApoA-1), LDL and HDL particles (LDL-P and HDL-P), small, dense LDL cholesterol (sdLDL-C), and Lipoprotein(a) [Lp(a)] may also be elevated and associated with atherosclerosis." (PMID 35300601, 2022). "Evidence for relevant implications of these cells in cardiovascular diseases exist in atherosclerosis, where Th1 and Th17 cells emerge in the development of atherosclerosis when autoreactive CD4+ T cells are stimulated with ApoB peptides in an environment of inflammatory cytokines." (PMID 35845058, 2022). "Furthermore, deletion of PCSK9 in mice resulted in decreased lipid and apoB levels and atherosclerotic LDL reduction, and reduced atherosclerosis." (PMID 36470666, 2022). "These liability traits/features, already apparent in childhood, include cholesterol and triglycerides within non-HDL particles that contain apolipoprotein B, which enables lipid-mediated atherosclerosis." (PMID 34499663, 2021). "In conclusion, our data suggests that AIRE is not involved in regulating thymic expression of ApoB or atherosclerosis." (PMID 35097028, 2021). "In this review, we highlight adaptive immune mechanisms in atherosclerosis with a focus on CD4+ T cells, introduce novel technologies to detect ApoB-specific CD4+ T cells at the single cell level, and discuss the potential impact of ApoB-driven autoimmunity in atherosclerosis." (PMID 33669769, 2021). "Yet, it is unclear whether AIRE controls the expression of ApoB and the autoimmune CD4+ T cell response in atherosclerosis." (PMID 35097028, 2021). "Experimental studies in atherosclerosis-prone mice have demonstrated that immunization with several atherosclerosis-related antigens, native LDL, oxidized LDL, or ApoB-derived peptides, induces antigen-specific Tregs and attenuates atherosclerotic lesion development." (PMID 34945203, 2021). "Apolipoprotein B (ApoB) is one of the main components of LDL-C, and it can promote the phagocytosis of oxidized LDL by macrophages and monocytes, which thereby transform into foam cells and induce atherosclerosis." (PMID 34627286, 2021). "Adoptive transfer of ApoB+ Tregs did not protect Apoe−/− mice from atherosclerosis progression, as the transferred cells likely lost their atheroprotective Treg phenotype." (PMID 33266027, 2020). "Apolipoprotein B, which is a component of LDL-C and TG, contributes to atherogenesis, although the protective role of HDL-C, which mainly includes apolipoprotein A1, on atherosclerosis has been described." (PMID 32752179, 2020). "The levels of total cholesterol, triglycerides, LDL, apolipoprotein A, apolipoprotein B, apolipoprotein E, lipoprotein A, total cholesterol/HDL, and LDL/HDL were all significantly different between patients with atherosclerosis etiology as compared to that with lacunar etiology." (PMID 33050269, 2020). "Future preclinical studies should analyse whether modified EVs loaded with a low expression of APOB and FL and an overexpression of LRP1 and MBL2 could reduce atherosclerosis formation." (PMID 33374290, 2020).
atherosclerosis (continued). "The absence of PCSK9 in LDb mice results in decreased lipid and apoB levels, fewer atherogenic LDLs, and marked reduction of atherosclerosis." (PMID 29180444, 2018). "A large number of studies have demonstrated that DKD and H. pylori infection may contribute to dyslipidemia by affecting ApoA1, ApoB, TG, TC, HDL, LDL, and oxidized LDL levels, and that these effects may promote the development of atherosclerosis." (PMID 29849820, 2018). "The cholesterol contained within apolipoprotein B (apo B) particles, also referred to as non-high-density lipoprotein cholesterol (non-HDL-C), is strongly associated with the pathogenesis of atherosclerosis." (PMID 27417914, 2016). "A kidney-tonifying herbal medicine “Semen Sesami Nigrum” could inhibit ApoB and reduce LDL protein to prevent atherosclerosis." (PMID 28031022, 2016). "Further, in another interesting study immunization with human HSP60 (with or without combination with apoB peptides) led to decreased atherosclerosis." (PMID 23635324, 2013). "Also an increased ApoB/ApoA1 ratio has a role in clinical CVD development, including subclinical atherosclerosis." (PMID 21692678, 2011). "Non-HDL, which is a carrier of apolipoprotein B, may also contribute to the development of atherosclerosis." (PMID 40149619, 2025). "The study enrolled 12,301 participants with either established atherosclerosis or high-risk diabetes, but no prior myocardial infarction or stroke with a baseline LDL cholesterol ≥ 90 mg/dL, non-HDL cholesterol ≥ 120 mg/dL, or apolipoprotein B ≥ 80 mg/dL, on optimized lipid-lowering therapy." (PMID 40172616, 2025). "For example, the genes contributing significantly towards h2RV of ApoB results in enrichment of 156 pathways, all of which are highly interconnected in an elaborate network and includes well-known pathways such as the LDL receptor binding pathways and pathways related to atherosclerosis." (PMID 38336875, 2024). "In brief, the variation of the ApoB/ApoA1 ratio arising from the progress of CHB disease is worth studying, and it can indirectly suggest the effect exerted by the progress of CHB disease on atherosclerosis, and add novel insights for the early diagnosis of LC and HCC." (PMID 38744926, 2024). "Though cholesterol deposition within the arterial lumen was regarded as a classic characteristic of atherosclerosis, it could not enter the arterial wall unless it was carried by apoB particles." (PMID 37559117, 2023). "Notably, anti-ApoB antibodies could help clearing LDL particles from the circulation or block its uptake by macrophages and prevent atherosclerosis." (PMID 35479271, 2022). "Through an immune intervention with specific Ox-ApoB fragments, we found that the damaging effects of Ox-LDL on the endothelial cell junction barrier were decreased, and the endothelial cell junction barrier was more protected, thereby inhibiting the progression of atherosclerosis." (PMID 35391927, 2022). "Cholesterol-rich LDL and other apolipoprotein B (ApoB)-containing lipoproteins, including very low-density lipoproteins (VLDL), intermediate density lipoproteins (IDL) and lipoprotein(a), m[Lp(a)], have a direct impact on the development of atherosclerosis and its cardiovascular consequences." (PMID 36003652, 2022). "Such ApoB-reactive (ApoB+) CD4+ T cells mainly comprise Tregs, which confer atheroprotective properties in healthy humans, but coexpress TFs typical of proatherogenic TH1 or TH17 cells in individuals with subclinical atherosclerosis as determined by carotid ultrasound." (PMID 35097027, 2021). "Levels of low-density lipoprotein (LDL), apolipoprotein B (ApoB), HDL, apolipoprotein A1 (ApoA1), and C-reactive protein (CRP) are significant biomarkers of vascular inflammation and are critical to almost all inflammatory disease processes including atherosclerosis." (PMID 33644628, 2021).
atherosclerosis (continued). "Low HDL-C levels; a total cholesterol to HDL-C (T-CHO/HDL-C) ratio greater than five; and high levels of LDL-C, triglycerides, non-HDL-C (total cholesterol minus HDL-C), and apolipoprotein-B (ApoB) are all conventionally considered biomarkers of atherosclerosis." (PMID 33923190, 2021). "Herein we crossed Aire- and apolipoprotein E (Apoe)-deficient (Aire−/−Apoe−/−) mice to test whether lack of AIRE would increase peripheral ApoB-reactive effector T cell numbers and functions and increase atherosclerosis." (PMID 35097028, 2021). "Presumable cross-presentation of LDL derived apolipoprotein-B100 (ApoB100) epitopes on MHC-I by lesional phagocytes, suggests that inducing ApoB100 specific CD8 T cells could lead to killing of lesional macrophages and reduce atherosclerosis." (PMID 31757993, 2019). "Considering AVS shares many other risk factors with atherosclerosis, participants with CAD may also already have established subclinical AVS, at which stage increased apoB/apoA‐I may not confer any additional risk for AVS incidence." (PMID 31407609, 2019). "According to the “infiltration theory,” the development of atherosclerosis is triggered by the entry and subendothelial retention of lipoprotein from the bloodstream, particularly low density lipoprotein (LDL), and apolipoprotein-B (apoB)-containing remnants within the arterial wall." (PMID 30320124, 2018). "Hence, appropriate interventions aimed at controlling weight and ALT and ApoB levels should be helpful because they could simultaneously prevent increases in CIMT and the early stages of atherosclerosis." (PMID 28220866, 2017). "Consistent with the hypothesis that a significant number of mechanisms underlying atherosclerosis and ACS without SMuRFs remains undiscovered, our study will be the first to elaborate metabolomic and inflammatory biomarkers, such as Lp(a), ApoB and ApoA1 interleukin-6 (IL-6) and suPAR." (PMID 36959584, 2023). "In patients exhibiting a discordance involving low LDL-C andhigh apolipoprotein B or non-HDL-C levels, an increased risk of arterialstiffness was observed, as measured by brachial-ankle pulse wave velocity; thesefactors are regarded as markers of subclinical atherosclerosis." (PMID 39076405, 2023). "To note, more than half of CD4+ T cells reactive to ApoB peptides express FoxP3 in individuals without cardiovascular disease but dramatically decrease and acquire the expression of RORγt and T-bet transcription factors in patients with subclinical atherosclerosis." (PMID 35966516, 2022). "Furthermore, few studies have shown better prediction by LDL-C, non-HDL-C, or apoB over the apoB/apoA-1 ratio for the amount of atherosclerosis based on calcium score, ultrasound measurements of the carotid and femoral artery, endothelial functions, or other CV measurements." (PMID 34851955, 2021). "However, CD4+ T cells recognizing epitopes derived from unmodified apolipoprotein B100 (ApoB) has also been found, first in human ApoB100 transgenic mice, and more recently in the blood from subjects with and without atherosclerosis, by using an MHC class II-tetramer loaded with an ApoB epitope." (PMID 33805071, 2021). "The fact that our study did not register a progressive decrease in the LDL-C/apoB ratio across the three groups does not fully contradict the theory of “LDL quality”, as atherosclerosis is a complex process in which cholesterol is only one of the main players." (PMID 41374382, 2025). "The Multi-Ethnic Study of Atherosclerosis (MESA) found that among patients without ASCVD not receiving LLT, discordant low apoB/high LDL-C and high apoB/low LDL-C patterns occurred in 9% and 8.4% of patients, respectively." (PMID 41517276, 2025). "Rabbit is one of the best models for the examination of human hyperlipidemia and atherosclerosis because rabbits possess CETP and intestinal apoB editing which like human but unlike mouse." (PMID 39087075, 2024).